CFB (complement factor B)
Description:
Precursor of the catalytic component of the C3 and C5 convertase complexes of the alternative pathway of the complement system, a cascade of proteins that leads to phagocytosis and breakdown of pathogens and signaling that strengthens the adaptive immune system. The alternative complement pathway acts as an amplification loop that enhances other complement pathways (classical, lectin and GZMK) by promoting formation of additional C3 and C5 convertases. CFB is cleaved and activated by CFD to generate Ba and Bb chains; Bb chain constituting the catalytic component of the C3 and C5 convertases. [Complement factor B Bb]: Serine protease component of the complement C3 and C5 convertase complexes of the alternative complement pathway. Following cleavage and activation by factor D (CFD), forms the C3 convertase together with complement C3b. As part of the C3 convertase, cleaves and activates C3 into C3a anaphylatoxin and C3b opsonin, the next components of the complement pathways. When an additional complement C3b molecule binds to the C3 convertase, forms the C5 convertase, which cleaves and activates C5 into C5a anaphylatoxin and C5b component of the membrane attack complex. [Complement factor B Ba]: Involved in proliferation and differentiation of preactivated B-lymphocytes, rapid spreading of peripheral blood monocytes, stimulation of lymphocyte blastogenesis and lysis of erythrocytes.
Synonyms: GBG; BF; BFD; H2-Bf; AHUS4; ARMD14; CFAB; CFBD; FB; FBI12; PBF2
Tractability: Small molecule: a drug acting on it is in phase 2 or 3 trials; a structure with a bound ligand is known; a high-quality ligand is known; it has a high-quality binding pocket. Antibody: UniProt places it where antibodies can reach, with high confidence; its Gene Ontology location is reachable by antibodies, with high confidence; UniProt predicts a signal peptide or a membrane-spanning region. PROTAC: ubiquitination databases record sites on it; a small molecule that binds it is known.
Target class: Serine protease; Enzyme; Serine protease PA clan; Serine protease S1A subfamily; Protease
Chemical probes: IPTACOPAN (high quality)
Gene: Protein-coding gene on chromosome 6 (31,945,650 to 31,952,086, forward strand). Ensembl gene ENSG00000243649.
Subcellular location: Secreted; Cell surface (Complement factor B Bb)
Subcellular location (Human Protein Atlas): Endoplasmic reticulum; Vesicles; Cell Junctions; Predicted to be secreted
Pathways (Reactome):
Immune System: Activation of C3 and C5; Alternative complement activation; Regulation of Complement cascade
Gene Ontology:
Molecular function: protein binding; serine-type endopeptidase activity; complement binding
Biological process: complement activation, alternative pathway; response to bacterium; complement activation; proteolysis
Cellular component: blood microparticle; cell surface; extracellular exosome; extracellular region; symbiont cell surface; plasma membrane
Genetic constraint (gnomAD): Loss-of-function variants: 60 observed, 103.53 expected, observed/expected ratio (o/e) 0.58, 90% interval 0.47 to 0.72. The upper end of that interval is the gene's LOEUF score, 0.72, which puts it in group 2 of 6, group 1 being the genes least tolerant of losing a copy. Missense variants: 771 observed, 1,010.5 expected, observed/expected ratio (o/e) 0.76, 90% interval 0.72 to 0.81. Synonymous variants: 316 observed, 371.61 expected, observed/expected ratio (o/e) 0.85, 90% interval 0.77 to 0.93.
Gene-disease validity (ClinGen):
ClinGen rates the evidence that CFB causes each of these diseases.
atypical hemolytic-uremic syndrome with B factor anomaly (autosomal dominant): Moderate.
C3 glomerulonephritis (autosomal dominant): Limited. Glomerulonephritis characterized by C3 accumulation with little or absent deposition of immunoglobulin, in the absence of ultrastructural electron-dense transformation seen in dense deposit disease.
Homologues: Orthologues: macaque CFB (94% identical), chimpanzee C2 (88% identical), rabbit CFB (84% identical), mouse Cfb (82% identical), dog CFB (79% identical), guinea pig CFB (79% identical), pig CFB (78% identical), tropical clawed frog cfb (40% identical), zebrafish cfb (37% identical), zebrafish cfbl (37% identical), zebrafish bfb (21% identical). Paralogues in human: C2 (38% identical), SEZ6L (16% identical), CSMD1 (15% identical), CSMD2 (15% identical), SEZ6 (15% identical), CSMD3 (15% identical), SEZ6L2 (14% identical), SVEP1 (12% identical), CR1 (11% identical), CR2 (9% identical), CFH (8% identical), C4BPA (7% identical), and 27 more.
Diseases named in the same sentence as CFB in open-access papers:
CFB is named in the same sentence as 193 diseases in open-access papers, as found by Europe PMC text mining. Sharing a sentence is not in itself a finding about the gene and the disease. The quoted sentences say what the papers report.
age-related macular degeneration (23 papers, 2008 to 2025). Age-related loss of vision in the central portion of the retina (macula), secondary to retinal degeneration. "Complement factor B (fB) is an essential activator protein in the alternative complement pathway, and variations in the fB gene are associated with age-related macular degeneration." (PMID 37560455, 2023). "Numerous genetic studies have demonstrated that rs12614 within CFB confers susceptibility to several immune and infectious diseases, such as age-related macular degeneration and chronic hepatitis B." (PMID 36311737, 2022). "Another gapmer in clinical trials, IONIS-FB-LRX, was designed to reduce complement factor B to treat geographic atrophy associated with age-related macular degeneration (AMD)." (PMID 34068948, 2021). "The genes containing the most significant SNPs for breast cancer ranged widely in apparent function with GWAS associations reported with SNPs in CFB (complement factor B) for age-related macular degeneration, BAZ2A for platelet counts and ACADS for metabolic traits." (PMID 23555315, 2013). "This was demonstrated by the finding that deficiency of alternative complement pathway (using CFB-/- mice) can ameliorate age-related macular degeneration (AMD) associated with smoking." (PMID 40612949, 2025). "The 32W and 32Q variants of complement factor B (CFB) are associated with reduced risk of developing neovascular age-related macular degeneration (AMD) compared with the common 32R allele." (PMID 32407521, 2020). "Recently, it was reported that CFB is involved in hypertension and has anticancer activity, due to inhibiting cell proliferation, migration, and age-related macular degeneration." (PMID 39941161, 2025). "A recent study among patients with intermediate age-related macular degeneration demonstrated higher levels of complement factor B and complement factor I in females as compared to males." (PMID 38385704, 2024). "The pathology of age-related macular degeneration (AMD) is suggested to be influenced by polymorphisms and/or substantially altered expression levels of complement factors, including complement factor B (CFB) and complement factor I (CFI), both of which are serine proteases." (PMID 31398819, 2019). "In genetic studies on age-related macular degeneration (AMD), its association with the CFH gene led to the discovery that other molecules in the complement pathway were also associated with the condition, such as C2/CFB, C3, and CFI." (PMID 23213273, 2012). "Our data could not demonstrate any significant association of the CFB rs4151667 (L9H) polymorphism with Age-related Macular Degeneration in Iranian patients." (PMID 32762675, 2020).
COVID-19 (16 papers, 2021 to 2024). A disease caused by infection with severe acute respiratory syndrome coronavirus 2. "Similarly, umbilical cords from COVID-19-affected pregnancies showed higher expressions of CFB and C4A compared to controls (Fig. EV1C)." (PMID 39390219, 2024). "In conclusion, transcription and activation of pathogenic complement can be normalized in epithelial cells using drugs that target JAK1, CFB or the virus itself and combinations of these may be therapeutically beneficial in treating COVID-19." (PMID 33827897, 2021). "In an independent (bulk) RNA-seq dataset of bronchoalveolar fluid cells from (n=8) patients with COVID-19 and (n=20) uninfected controls, we found similar enrichment of complement genes in cells from patients, including significantly higher expression of C3 and CFB." (PMID 33827897, 2021). "Some genes that may be related to severe COVID-19 pathophysiology and are good candidates for experimental investigation include PRKG1, ACE, CFB, CRP, CTNNB1, EGFR, and VEGFA." (PMID 35794133, 2022). "The top five targets identified based on candidate gene prioritization were C3, CFB, EGFR, IL6, and TLR2, where the 39 common core genes were used as a test set, and 1899 genes from the COVID-19 pathway (KEGG) and our multi-omics datasets were used as training sets." (PMID 34067609, 2021).
breast cancer (15 papers, 2008 to 2026). A primary or metastatic malignant neoplasm involving the breast. "The levels of complement factor B has been shown to be increased in breast cancer and associated with molecular subtypes of breast cancer." (PMID 28650989, 2017). "In addition, CFB has emerged as a prognostic marker in breast cancer, with elevated expression being associated with a favorable prognosis." (PMID 39495117, 2024). "Next, we confirmed that macrophage-derived CXCL1/2 and CFB were upregulated in tumors, liver and lung tissues, as well as serum from mice orthotopically inoculated with 4T1 breast cancer cells after Dox treatment by immunofluorescence staining and ELISAs." (PMID 41480760, 2026). "Overall, cytokines (excepting CCL7 in the breast cancer and CFB in the prostate cancer system, respectively) are upregulated under both transwell and mixture conditions." (PMID 31963450, 2020). "Hence, we examined the xenobiotic metabolism-associated genes (PYCR1, KYNU, CFB, HMOX1 and HES6) expressed in both breast cancer cells and in normal mammary epithelial cells." (PMID 37845207, 2023). "CFB is stably upregulated in various cancer tissues, and in studies of adenocarcinoma, this gene has been shown to alleviate cancer progression by activating cellular immune responses, consistent with the trend of this study in predicting progression of breast cancer." (PMID 36267313, 2022). "Together, these data suggest that macrophage-derived CXCL1/2 and CFB serve as key drivers of neutrophil aggregation and NET formation in breast cancer following chemotherapy and radiotherapy." (PMID 41480760, 2026). "Conversely, inflammatory proteins, such as complement C3, complement C9, complement factor B, and complement 4B, were significantly elevated in TNBC patients, suggesting a shift toward a pro-inflammatory HDL-C phenotype in aggressive breast cancer." (PMID 40430118, 2025). "In breast cancer datasets, the five most important mRNAs were GABARAP, PFDN5, RPL21, CFB, and PCED1A." (PMID 39495117, 2024). "Moreover, expression of top five genes (NCEH1, RARRES3, NTN4, CFB and CYP4Z1) that are frequently co-expressed with TNFSF10 in breast cancer patients, have been detected upon transfection with miR-7641 mimic." (PMID 28827731, 2017). "Breast cancer patients were reflective of their differential expression of serum α1-antichymotrypsin (ACT), clusterin (CLU) and complement factor B (CFB), while patients with nasopharyngeal carcinoma expressed the sole elevated levels of serum ceruloplasmin (CPL)." (PMID 18637207, 2008). "Similarly, the CFB antagonist iptacopan (LNP023) has demonstrated efficacy and good tolerability in an ongoing phase III trial for IgA nephropathy, suggesting promising application in breast cancer." (PMID 41480760, 2026). "In line with the results from the breast cancer model, BST2 was not significantly deregulated in the transwell experiment, whereas the complement factor B (CFB) was 6-fold overexpressed under these conditions." (PMID 31963450, 2020).
diabetes (11 papers, 2013 to 2025). "CFB mRNA was also clearly up-regulated in isolated pancreatic islets of all tested animal models of diabetes: Akita and db/db mouse models for phenotypes associated with T1D and T2D, respectively, and BB and GK rats, which correspond to T1D and T2D models." (PMID 38346191, 2024). "A final multivariable model found three proteins (Contactin-5 [CNTN5], Low affinity immunoglobulin gamma Fc region receptor II-a [FCGR2A], and Complement factor B [CFB]) associated with incident CVD after adjustment for diabetes (AUC = 0.82)." (PMID 33441605, 2021). "CFB (complement factor B) is elevated in adipose tissue and serum from patients with type 2 diabetes mellitus and cardiovascular disease, but the causal relationship to disease pathogenesis is unclear." (PMID 28739975, 2017). "CFB is elevated in human cohorts with type 2 diabetes mellitus and cardiovascular disease, although a causal relationship has yet to be established." (PMID 28739975, 2017). "We now show that CFB is also significantly up-regulated in isolated islets of several rodent models of diabetes, is secreted from isolated human islets, where it becomes cleaved to Bb, a sign of activation." (PMID 38346191, 2024). "One of the differentially abundant proteins (complement factor B) was identified as a biomarker for diabetes after sorting against the list of proteins identified to be involved in diabetes, as indicated in the peptide atlas database." (PMID 36876056, 2022). "Complement factor B (CFB) plays a significant role in the pathogenesis of diabetic retinopathy, and there might be a relationship between CFB and diabetes onset." (PMID 35328013, 2022). "The human CFB locus—a gene-rich region within the major histocompatibility complex—contains several GWAS hits for cardiometabolic traits, including coronary heart disease, blood pressure, MetS, type 2 diabetes mellitus, serum lipids, and visceral fat." (PMID 28739975, 2017). "Replication analysis conducted on 385 IA cases from The Environment Determinants of Diabetes in the Young (TEDDY) study confirmed 68 significant (FDR < 0.05) pQTLs in total for C8A, C8B, CFB, C4A, and MBL2." (PMID 39989961, 2025). "Then, in streptozotocin-induced (STZ-induced) type 1 diabetic mice and db/db mice, which developed albuminuria 3 months and 6 months after diabetes mellitus (DM), obvious induction of CFB, C3d, C5b-9, and C5aR was observed in the glomeruli 6 months after DM by immunohistochemical staining." (PMID 34622800, 2021).
IgA nephropathy (10 papers, 2019 to 2026). "CFB is targeted by the antisense oligonucleotide Sefaxersen, in development for IgA nephropathy." (PMID 41413375, 2025). "Currently, several clinical trials are assessing the efficacy of selective complement inhibitors in IgA nephropathy, with promising results showing a reduction in proteinuria and inhibition of route-specific complement activation reported for CFB and MASP-2 inhibitors." (PMID 38046006, 2023). "Furthermore, the two patients who had elevated serum levels of Bb fragment of complement factor B also showed histological signs of a previously unknown IgA glomerulonephritis without active lesions, but with severe glomerulosclerosis." (PMID 39596538, 2024).
atypical hemolytic-uremic syndrome (8 papers, 2011 to 2022). A rare, genetic thrombotic microangiopathy due to dysregulation of the alternative complement pathway and characterized by the triad of hemolytic anemia, thrombocytopenia, and acute renal dysfunction. "In addition, CFB cleavage is abrogated in aHUS (atypical hemolytic uremic syndrome) patients’ serum when using danicopan, which is an oral CFD inhibitor." (PMID 36582241, 2022). "In addition, CFB polymorphisms were also found to be associated with other inflammatory diseases, such as AMD, lupus, and atypical Hemolytic-uremic syndrome (aHUS)." (PMID 23864767, 2013).
lung carcinoma (8 papers, 2014 to 2024). "For instance, it was reported that high expression of CFB was associated with increased patient overall and disease-free survival in lung cancer patients." (PMID 36613598, 2022). "Mutations in the CFB gene cause reduced activation of B cells, resulting in changes in the tumor immune environment, potentially playing a role in its correlation with unfavorable outcomes in breast and lung cancer." (PMID 38751445, 2024). "In lung cancer and in pancreatic adenocarcinoma, low CFB expression correlated with the presence of more aggressive tumours and a worse overall survival; consistently, in our cohort, SS showed the lowest CFB expression." (PMID 37761312, 2023). "FCGBP, BPIFB1, F5, CFB, and CST1 and their correlation to EMT key markers displayed a potentially less metastatic phenotype of lung cancer under SMG." (PMID 36613598, 2022). "We highlight the increased expression of immune-response-related genes FCGBP, BPIFB, F5, CST1, and CFB, and their correlation to epithelial-to-mesenchymal transition (EMT) under SMG, rendering them potential biomarkers of lung cancer progression." (PMID 36613598, 2022). "Overall, these data imply that the differentially expressed FCGBP, F5, CFB, and BPIFB1 in lung cancer may play an important role in lung cancer progression." (PMID 36613598, 2022). "Given its route of transmission and tropism for alveolar macrophages, factors that have not been previously reported appear to be relevant to OPPV disease, such as lung cancer biomarker (SAA1), asthma biomarker (CHI3L1), and neuro-inflammation complement factor (CFB)." (PMID 26950733, 2016).
Sepsis (7 papers, 2015 to 2026). Sepsis is defined as life-threatening organ dysfunction caused by a dysregulated host response to infection. "In the kidneys, the alternative pathway plays an important role in the pathogenesis of lupus nephritis, and the CFB may decrease specific sodium transporter expression during sepsis." (PMID 39941161, 2025). "Also, splenic RNA and miR‐146a are released into the circulation during polymicrobial sepsis and promote the production of complement factor B via TLR7 signaling." (PMID 28665028, 2017). "This suggested to the researchers that CFB, acting outside of the alternative pathway, is a downstream effector of Toll-like receptors (TLRs) and plays an important role in the mouse model of severe sepsis." (PMID 26420913, 2015). "The most modulated genes were Granzyme B, Complement Factor B, Complement Component 4 Binding Protein Alpha, IL-12, and SERPINB-1 that were closely related to sepsis-induced immunological process." (PMID 33868226, 2021). "CFB is a necessary component of the Complement alternative pathway and an important downstream effector of TLR signaling in sepsis." (PMID 33868226, 2021). "This is the first study examining urine complement factor B fragments in patients with and without sepsis in a moderately sized cohort of critically ill children." (PMID 36758197, 2023).
lupus (6 papers, 2013 to 2025). "To understand whether renal tubule changes associate with lupus disease progression, we performed immunostaining of CFB and C3." (PMID 37047136, 2023). "Conversely, experimental deletion of other essential cAP components, such as complement factor B or factor D, significantly reduces renal injury severity in murine lupus models." (PMID 41019087, 2025).
asthma (5 papers, 2014 to 2025). "Of these genes, CFB was induced in all patients, whereas BMP6 solely in allergic rhinitis patients and MYLK in allergic rhinitis patients with asthma." (PMID 24475887, 2014).
hemolytic-uremic syndrome (5 papers, 2016 to 2023). Acute kidney injury associated with microangiopathic hemolytic anemia and thrombocytopenia. "Pathogenic gain-of-function variants in complement Factor B were identified as causative of atypical Hemolytic Uremic syndrome (aHUS) in 2007." (PMID 34721423, 2021). "As an example, patients diagnosed with atypical Hemolytic Uremic Syndrome and with a positive genetic report identifying pathogenic variants in CFH, C3 or CFB genes, are at moderate to high risk of recurrence after transplantation." (PMID 36782285, 2023).